EGFR (epidermal growth factor receptor)
Diseases named in the same sentence as EGFR in open-access papers (continued):
Sharing a sentence is not in itself a finding about the gene and the disease.
cancer (continued). "Cancer cells often proliferate in response to signaling from Receptor Tyrosine Kinases (RTKs), and the effect of magnetic fields on EGFR phosphorylation was the subject of several studies." (PMID 27223425, 2016). "Studies have shown FAM83 proteins interact with many key cancer-signaling proteins including EGFR (FAM83B), PI3K (FAM83A-B), AKT (FAM83B), c-RAF (FAM83A-E)." (PMID 27221039, 2016). "In our group, we have developed a quantitative PCR technique in the presence of PNA to detect EGFR, KRAS, and BRAF mutations in the cfDNA of advanced lung, colon, and cancer patients that achieves 75–80% sensitivity with 100% specificity." (PMID 28066769, 2016). "Humanized antibodies and small-molecule inhibitors targeting EGFR were developed to disrupt these functions in cancer cells and are currently used in the treatment of diverse metastatic epithelial cancers." (PMID 27322144, 2016). "Molecular targeted therapies for specific genomic alterations, such as epidermal growth factor receptor (EGFR) mutations and anaplastic lymphoma kinase (ALK) gene rearrangements, are among the greatest innovations in the field of personalized cancer therapy." (PMID 27050074, 2016). "Although it is accepted that the NF-κB plays many important roles in cancers, its connection with the other critical oncogenic pathways downstream of EGFR activation in HNSCC is still unclear." (PMID 26895469, 2016). "After human SCCHN tissue samples were incubated with Pan‐IR700, fluorescence histology demonstrated a strong correlation between fluorescence, EGFR expression, and cancer, and did so in a dose‐dependent manner." (PMID 27167827, 2016). "We searched for mutations in 22 cancer-related genes, using target sequencing techniques to further characterize the 12 patients who had AXL 3+ expression, of whom 6 had mutations in EGFR, 2 in KRAS, and 1 EML4–ALK fusion gene." (PMID 27100677, 2016). "Due to the lack of intrinsic kinase activity, the importance of HER3 signaling in cancer was not recognized until it was shown to have an important role in acquired resistance to EGFR targeting cancer therapies." (PMID 27582551, 2016). "In normal cells, EGFR plays an essential role in e.g. organogenesis, but structural alterations as well as overexpression of EGFR is seen in many types of cancer." (PMID 26844548, 2016). "In this regard, a prior analysis using more than 200 published studies that had examined relapse-free-interval or survival data directly in relation to EGFR levels in over 20,000 patients found elevated EGFR levels in cancer cells of clinical prognostic value." (PMID 30370422, 2016). "Our results show that miR-217-CAGE feedback loop serves as a target for overcoming resistance to various anti-cancer drugs, including EGFR and HER2 inhibitors." (PMID 26863629, 2016). "The areas of highest fluorescence were shown to co‐localize with areas of high EGFR expression and cancer‐containing tissue (Odyssey, LI‐COR)." (PMID 27167827, 2016). "Accordingly, epidermal growth factor receptor (EGF-R) inhibitors appear to provide synergy with BRAF inhibitors in multiple BRAF-mutant cancers." (PMID 26942566, 2016). "c-MET and epidermal growth factor receptor (EGFR) are well-known tyrosine receptor kinases that are coexpressed in multiple cancers, including GBM." (PMID 26700818, 2016). "In multivariate logistic regression analysis, NSCLC patients with GLK-High had high risks of cancer recurrence (n = 58, OR = 9.98, 95% CI, 2.24–44.5, P = 0.003) after adjusting for the pathologic stage, smoking status, alcohol status, and EGFR protein levels." (PMID 27203390, 2016). "People have tested a liposomal nanoparticle loaded with synthetic miRNA-34a mimics (MRX34) that against cancer cells when combined with the EGFR-TKI Erlotinib treatment." (PMID 27790245, 2016). "This is why, EGFR targeting was conceived to be a successful strategy to increase anti-cancer treatment efficacy." (PMID 30370422, 2016).
cancer (continued). "The EGFR is overexpressed in most human cancers, including breast cancer, cervical cancer, and lung cancer." (PMID 28053990, 2016). "It is an oncoprotein, as are multiple proteins in the EGFR signaling pathway, and several EGFR signaling inhibitors have been approved for cancer treatment." (PMID 27223425, 2016). "EGFR has been shown to play essential roles in cell proliferation, survival, and migration as well as in carcinogenesis and cancer progression, and is considered an attractive target for anticancer therapies." (PMID 27711202, 2016). "Taken together, these results indicate that the signaling from integrin and EGFR contributes to therapy resistance, a phenomenon that has also been observed in other cancer cells." (PMID 26728650, 2016). "Inhibition of the EGFR/Akt pathway induces cellular senescence and suppresses the cancer stem cell phenotype in NPC cells." (PMID 27203742, 2016). "Epidermal growth factor receptor (EGFR) is a well-known oncogene that plays a key role in multiple cancers." (PMID 27011181, 2016). "The EGFR and survivin pathways represent two independent while interacting survival mechanisms in many cancer cells." (PMID 27456457, 2016). "The use of these combined therapies was shown to be a good therapeutic option to either prevent or overcome resistance to TAM in cancers overexpressing epidermal growth factor receptor (EGFR) or EGFR2 (HER2)." (PMID 27548161, 2016). "Because EGF can strongly bind EGFR, which is overexpressed in cancer cells, the targeting ability of the SPACE-EGF-siRNA complex is increased." (PMID 27374619, 2016). "Over-expression and constitutive activation of EGFR have been found in numerous human cancers, including breast, lung and head and neck carcinomas." (PMID 27245053, 2016). "The expression level of EGFR was commonly upregulated in many cancers, for instance, colon, ovarian, breast, and lung especially." (PMID 27830146, 2016). "The results suggest that the silencing of EGFR and survivin by PSEP is associated with activated apoptotic signaling in PSMA-positive cancer cells." (PMID 27456457, 2016). "In this review, we have summarized the available data and discussed potential clinical importance of the anti-EGFR immune responses and EGFR-mediated immune regulation in cancer." (PMID 27833557, 2016). "Here in this study we focus our study on EGFR overexpressing cells (CHO-EGFR cells and the EGFR overexpressing cancer cell lines)." (PMID 27223425, 2016). "Other studies have reported that EGFR mutations were correlated with GGO components, although those studies typically examined early-stage cancers." (PMID 27518729, 2016). "CAR10 up-regulated the expression of YB-1 by the direct binding and inhibition of its proteasomal degradation, resulting in an up-regulation of EGFR/pEGFR, pAKT and pERK, and a promotion of cancer cell proliferation in vitro and in vivo." (PMID 27322209, 2016). "Overexpression of EGFR and/or up-regulation of EGFR phosphorylation signaling are common in both cancers, with Akt playing a central role as the downstream effector molecule." (PMID 27793011, 2016). "MTLn3 cells are a prime example of cancer cells with upregulated EGFR and currently uses as an excellent cell model for invasion." (PMID 27256981, 2016). "The cancer cells acquire resistance to EGFR-TKIs and grow out of control with the activation of the cell cycle." (PMID 27825114, 2016). "Gefitinib reverts these effects, confirming a possible role of EGFR in regulating cancer cell adhesion." (PMID 27196940, 2016). "We observed crosstalk between Nrf2 and EGFR signaling in this model, providing important insights into cancer progression." (PMID 26904167, 2016). "Understanding naturally occurring ways of downregulating EGFR in cancer cells is under intense investigation." (PMID 27256981, 2016).
cancer (continued). "TAAs can be neoantigens, arising as a result of processed cancer-specific mutant peptides, or aberrant self-antigens like mesothelin or epidermal growth factor receptor (EGFR), due to overexpression of oncogenic proteins." (PMID 27762323, 2016). "Most epithelial tumors overexpress the EGFR and their activation is related with cancer progression." (PMID 27449755, 2016). "Further validation studies to test these secondary combination strategies to combat EGFR-TKI drug resistance emergence promise to further optimize cancer precision therapy by enhancing the duration of therapy response and impacting long term clinical outcome." (PMID 27852038, 2016). "A better understanding of septin contribution to the abnormal persistence of EGFR and ErbB2 in cancer cells will provide a potential treatment target for aggressive malignancies." (PMID 28066764, 2016). "Taken together, peptides P19 and P26 are potential vaccine candidates for the treatment of cancers with EGFR overexpression." (PMID 27659529, 2016). "EGFR is overexpressed in several cancers including, breast, ovarian, brain and colorectal, and this has led to development of specific TKIs directed against EGFR." (PMID 27552105, 2016). "To investigate the therapeutic potential of strong SMFs, we next examined effects on two human cancer cell lines that express EGFR, HCT116 and CNE-2Z." (PMID 27223425, 2016). "With a wide spectrum of aggressive cancers and minimal therapeutic options, development of effective therapeutics against EGFR-expressing cancers has become a major field of study." (PMID 27153091, 2016). "A subset of NSCLCs harbour activating mutations in the epidermal-growth factor receptor EGFR and respective small molecule inhibitors (EGFRi) are potent first line cancer drugs for this NSCLC subtype." (PMID 27063839, 2016). "EGFR is overexpressed in several human cancers and its overexpression correlates with poor prognosis in a large number of malignancies, including NSCLC." (PMID 26919248, 2016). "EGFR (ERBB1) and HER2 (ERBB2) are members of a tyrosine kinase receptor family frequently activated in cancer either by receptor overexpression or mutations." (PMID 27387915, 2016). "Experiments employing CAGE-binding peptide showed the importance of EGFR activation in anti-cancer drug resistance conferred by CAGE." (PMID 26863629, 2016). "The fact that PA increased the expression of EGFR protein and enhanced its phosphorylation strongly indicates that the reported carcinogenic capability of PA in various types of cancers is likely occurring through activation of EGFR tyrosine kinase." (PMID 27287039, 2016). "MAPKs are the intracellular effectors of ErbB receptors (EGFR, ErbB2, ErbB3 and ErbB4), and hyperactivation of the ERK1/2 MAPK signaling pathway frequently occurs in human cancer and is associated with increased cell survival and proliferation." (PMID 26843616, 2016). "It enabled targeted delivery of a high 111In payload specifically to EGFR-positive cancer cells leading to radiotoxicity that can be exploited for molecularly targeted radiotherapy." (PMID 26999580, 2016). "Multiple signaling pathways, such as PI3K/Akt/mTOR, mitogen-activated protein kinase, and Wnt/β-catenin, are activated by EGFR to enhance proliferation, survival, invasion, and metastasis of cancer cells." (PMID 27034004, 2016). "They further found the resistance mechanisms to ALK TKIs mediated by both ALK and by a bypass signaling pathway mediated by EGFR, and these mechanisms can occur independently, or in the same cancer." (PMID 27386342, 2016). "Epidermal growth factor receptor (EGFR), one of the cell surface biomarkers for targeting in Ab-based cancer therapy, is a transmembrane receptor protein embedded in the plasma membrane of many types of cells." (PMID 27877887, 2016). "In this study, we found that lapatinib, a dual tyrosine kinase inhibitor of HER2 and EGFR, induced significant cancer cell apoptosis in TNBC." (PMID 26824320, 2016).
cancer (continued). "EGFR has been received great attention in cancer research because of its connection to cancer development." (PMID 27881077, 2016). "The epidermal growth factor receptor (EGFR) is overexpressed in many cancers including lung, ovarian, breast, head and neck and brain." (PMID 27552105, 2016). "In summary, our data support the possibility of quercetin as an efficientanti-cancer agent in EGFR-overexpressing HNSCC." (PMID 27510965, 2016). "This anti-apoptotic effect of EGFR is mediated by the MAPK/ERK kinase (MEK)/MAPK signaling pathway in many types of normal cells as well as cancer cells." (PMID 27888617, 2016). "One such promising compound is honokiol, which has been shown to inhibit EGFR in various cancer models and potentiated the anticancer effects of EGFR tyrosine kinase inhibitors without any side effects." (PMID 27458163, 2016). "Pathological expression of EGFR has been observed in many cancers including head and neck, breast, pancreatic, non-small cell lung cancer (NSCLC) and colorectal cancers." (PMID 27552105, 2016). "On one hand, autophagy induced by EGFR-TKI acts as a cytoprotective response in cancer cells, and autophagy inhibitors can enhance the cytotoxic effects of EGFR-TKI." (PMID 27666552, 2016). "Cetuximab, an epidermal growth factor receptor (EGFR) monoclonal antibody that was widely used for cancer therapy, was exerted to block EGF/EGFR pathway." (PMID 27888616, 2016). "In this study, we show that miR-217-CAGE feedback loop regulates the response to various anti-cancer drugs, such as taxol, gefitinib, cetuximab and trastuzumab, through regulation of EGFR activation and CAGE interactions with EGFR and HER2." (PMID 26863629, 2016). "When DiFi cells were co-cultured with fibroblasts, the cancer cells maintained phosphorylation of EGFR and ERK1/2 despite treatment with gefitinib." (PMID 27121052, 2016). "Our findings provide critical insights into the role of EGFR-Axl hetero-dimerisation in cancer cells and reveal regulation of cell invasion via Axl as a novel function of EGFR signalling." (PMID 27775700, 2016). "Further, by applying multiple techniques including flow cytometry, immunohistochemistry and immunofluorescence, the underlying molecular mechanism of Asp-UA on the EMT and EGFR-mediated signaling pathways in MCF-7 and MDA-MB-231 cancer cells were explored." (PMID 27683033, 2016). "In present survey, we found that the phosphorylation of EGFR, a critical tyrosine kinase in the genesis and development of numerous human cancers, was suppressed by PA treatment." (PMID 27830146, 2016). "Since the PI3K/Akt pathway is one of the main signaling pathways downstream of EGFR, we examined the link between dysregulated EGFR signaling and cancer cell migration." (PMID 27102434, 2016). "Activation of EGFR-Raf-MAPK/ERK kinase-ERK signaling has been reported in several cancers, including HNSCC, and has led to the discovery of novel anticancer drugs." (PMID 26497678, 2016). "Focusing on sialic acid, increased levels of this sugar observed in certain cancer cell lines were found several years ago to inhibit EGFR activity in lung cancer cells." (PMID 27613843, 2016). "Previous studies have confirmed that FOXM1 was a downstream cellular target of EGFR signaling and had an important role in cancer development." (PMID 27494877, 2016). "While many factors are involved in the progression of GC, aberrant expression of epidermal growth factor receptor (EGFR) and its cognate ligands (e.g. EGF and AREG) is one of the major causes for malignancy progression and cancer formation." (PMID 27713123, 2016). "Yet notwithstanding their undisputed relevance to cancer, it is a well-known fact that EGFR, HER2 and ER are all expressed in normal cells, in which they play critical roles in normal cell growth and differentiation." (PMID 27768738, 2016).
cancer (continued). "806-PE38 displayed 1000-fold higher inhibition of cell viability over the parental m806 antibody or an anti-EGFR antibody, demonstrating the increase in anti-cancer potency offered by immunotoxin cytotoxic activity over signaling inhibition alone." (PMID 27153091, 2016). "Target therapy, such as anti-angiogenic therapy in treatment of NSCLC or anti-EGFR therapy has shown to improve survival of patients, but tumor resistance develops quickly in certain cases leading to cancer recurrence." (PMID 27362259, 2016). "Despite the widespread overexpression of EGFR in cancer, EGFR-targeted therapies have produced only modest clinical responses in patients." (PMID 27187360, 2016). "Epidermal growth factor receptor (EGFR) is an important oncogenic protein in multiple types of cancer." (PMID 27034618, 2016). "The Epidermal growth factor receptor is one of the highly investigated molecules in the pursuit of cancer-centric research to understand molecular regulation of the cancer cell survival and plasticity." (PMID 30370422, 2016). "The chimeric mouse–human IgG1 monoclonal antibody, Cetuximab, is an anti-human epidermal growth factor receptor (EGFR) antibody used for the treatment several cancers." (PMID 27459092, 2016). "Use of an EGFR tyrosine kinase inhibitor (TKI) is now a part of standard care in biologically appropriate subsets in cancers of the lung, colon and head and neck." (PMID 26909593, 2016). "In a preclinical study involving three human cancer cell lines with low, moderate, or very high EGFR expression, the extent of erlotinib-induced radiosensitization was proportional to the EGFR expression level." (PMID 28087951, 2016). "Unfortunately, the therapeutic inhibition of EGFR results in cancer regressions in only 10% to 20% of NSCLC patients." (PMID 27203390, 2016). "Recently, another study demonstrated that galectin-3 knockdown potentiates the response to gefitinib (EGFR-tyrosine kinase inhibitor) treatment in esophageal squamous cancer cells, a type of cancer that overexpresses EGFR." (PMID 27242966, 2016). "Previous study suggested that the inhibition of EGFR/Akt signalling significantly suppresses cancer cell metastasis, including NPC metastasis." (PMID 27793011, 2016). "As the aberrant activation and over expression of EGFR leads to the dysregulation of signaling functions in cell proliferation, survival and cancer progression." (PMID 27655695, 2016). "The epidermal growth factor receptor (EGFR) is a key cell surface receptor frequently up-regulated or overexpressed in cancer." (PMID 28933410, 2016). "There are evidences that cancer with moderate expression of EGFR are more sensitive to CTX compared with those that express very high levels of EGFR." (PMID 27884140, 2016). "It is well known that MAPKs play pivotal roles in carcinogenesis and that the MAPK pathway is a key downstream signaling pathway regulated by epidermal growth factor receptor (EGFR) signaling in a number of cancers." (PMID 26497678, 2016). "Wild-type EGFR has been shown to be a client protein of HSP90 suggesting that their interaction is vital for the proliferation of EGFR-dependent cancers." (PMID 26627081, 2016). "We therefore investigated the adjuvant effect of PFL in combination with EGFR inhibiting anti-cancer drugs currently in clinical use." (PMID 26850110, 2016). "PKP2 is an activator of epidermal growth factor receptor, and its overexpression is related to cancer malignancy." (PMID 27625789, 2016). "As with virtually all anti-cancer drugs, chronic exposure to EGFR inhibitors eventually induces molecular changes that confer varying degrees of drug resistance." (PMID 27716204, 2016). "In this study, the inverse correlation between EGFR and ZNF216 expression was confirmed in various human cancer cell lines differently expressing EGFR." (PMID 27732953, 2016).